ARL3 (ARF like GTPase 3)
Diseases named in the same sentence as ARL3 in open-access papers (continued):
Sharing a sentence is not in itself a finding about the gene and the disease.
glioma (continued). "In this study, we aimed to explore ARL3 expression and its roles in glioma prognosis." (PMID 31234870, 2019). "Furthermore, low ARL3 expression was related to adverse outcomes and radiation and chemotherapy resistance in glioma." (PMID 31234870, 2019). "Then, 46 clinical glioma samples were used to examine ARL3 expression in glioma by IHC." (PMID 31234870, 2019). "We also constructed a nomogram with ARL3 to predict 3- or 5-survival for glioma patients." (PMID 31234870, 2019). "Furthermore, low expression of ARL3 was related to adverse outcomes and radiation and chemotherapy resistance in glioma." (PMID 31234870, 2019). "Therefore, we speculated that overexpression of RP2 may also affect the progression of glioma through the interaction with ARL3." (PMID 37602882, 2023). "In addition, we explored the biological functions and pathways affected by ARL3 in glioblastoma, which may provide novel insights into glioma treatment." (PMID 31234870, 2019). "Therefore, ARL3 was chosen for further exploration in glioma." (PMID 31234870, 2019). "The results confirmed that ARL3 expression was downregulated in grade IV and grade III glioma samples." (PMID 31234870, 2019). "In view of the biological processes of ARL3 in GBM, we concluded that ARL3 plays an important role in the glioma immune microenvironment and angiogenesis." (PMID 31234870, 2019). "Thus, ARL3 may be a prognostic marker and therapeutic target for glioma." (PMID 31234870, 2019).
retinal disease (4 papers, 2021 to 2023). "A recent flurry of papers identified multiple Arl3 variants that cause either dominant or recessive retinal disease." (PMID 36598133, 2023). "Patients with heterozygous missense variant (c.269A>G, p.Tyr90Cys) in ARL3 have recently been found to cause non-syndromic autosomal dominant RP, confirming earlier reports of this missense variant causing retinal disease." (PMID 33748123, 2021). "The role of ARL3 in retinal disease was first noticed when it was identified as an RP2 interacting protein." (PMID 34485303, 2021).
cone-rod dystrophy (3 papers, 2021 to 2025). Inherited retinal dystrophies that belong to the group of pigmentary retinopathies. "Conversely, the ARL3-R99I variant affects ARL3 stability, and is associated with autosomal recessive cone-rod dystrophy, presumably by acting as a hypomorphic allele." (PMID 40037334, 2025). "However, in a recent study, a novel missense variant p.(Arg99Ile) in ARL3 has been described, resulting in a cone-rod dystrophy." (PMID 33805381, 2021). "Recently, cone/cone-rod dystrophy was also described in patients harbouring mutations in TTLL5 (tubulin tyrosine ligase like-5) and ARL3 (Arf-like protein 3), both interacting partners of RPGR." (PMID 33805381, 2021). "We found a family with rod-cone dystrophy (RCD) and verified it was associated with compound heterozygous variants in ARL3 gene." (PMID 33748123, 2021).
autosomal dominant retinitis pigmentosa (2 papers, 2016 to 2021). Autosomal dominant retinitis pigmentosa (RP) is an autosomally dominant inherited retinal dystrophy leading to progressive loss of the photoreceptors and retinal pigment epithelium and resulting in blindness usually after several decades. "Until functional studies are performed or additional families with ARL3 variants are identified, this gene will remain a candidate for autosomal dominant retinitis pigmentosa." (PMID 26964041, 2016).
hepatocellular carcinoma (2 papers, 2022). A malignant tumor that arises from hepatocytes. "In HBV-positive hepatocellular carcinoma (HBV+ HCC), DC1 bound to m6A-modified circ-ARL3 and favored its reverse splicing and biogenesis." (PMID 35351856, 2022).
breast carcinoma (1 paper, 2025). "Integrating our subsequent results, the combined transcriptomic and proteomic profiling disclosed that ARL3 deficiency induces metabolic reprogramming in HR+ breast cancer." (PMID 41047477, 2025). "This study identifies ADP‐ribosylation factor‐like protein 3 (ARL3) as a novel chaperone that stabilizes estrogen receptor α (ERα) in breast cancer." (PMID 41047477, 2025). "Capitalizing on ARL3's established roles in driving oncogenesis, metastasis, and endocrine resistance in hormone receptor‐positive (HR+) breast cancer, we pursued pharmacological targeting of this pathway." (PMID 41047477, 2025). "Collectively, these results establish ARL3 as a critical regulator of HR+ breast cancer progression, mediating cell proliferation, migration, and endocrine therapy sensitivity." (PMID 41047477, 2025). "Taken together, our data demonstrate that ARL3 exerts its biological effects in HR+ breast cancer through post‐transcriptional regulatory mechanisms of ERα." (PMID 41047477, 2025). "Given the central role of endocrine therapy in HR+ breast cancer management, we evaluated the sensitivity of ARL3‐modified cells to tamoxifen, a first‐line endocrine agent." (PMID 41047477, 2025). "In conclusion, our findings establish a mechanistic framework for ARL3‐dependent oncogenesis in HR+ breast cancer, highlighting its potential as both a biomarker of endocrine resistance and a druggable target for innovative therapeutic strategies." (PMID 41047477, 2025). "For elucidating the mechanisms by which ARL3 affects the progression of HR‐positive breast cancer, we conducted RNA‐sequencing (RNA‐seq) on ARL3‐knockout (ARL3‐KO) and isogenic control MCF7 cells, followed by functional enrichment analysis." (PMID 41047477, 2025). "Consistent with clinical observations, ARL3 mRNA and protein levels were selectively elevated in ERα‐positive breast cancer cell lines compared to normal mammary epithelial cells." (PMID 41047477, 2025). "Wound‐healing and transwell migration assays further showed that ARL3 downregulation impaired breast cancer cell motility, while ectopic ARL3 expression enhanced migratory capacity." (PMID 41047477, 2025). "Prognostic meta‐analysis using GEPIA and KM plotter demonstrated that elevated ARL3 expression correlates with significantly shorter overall survival in pan‐breast cancer cohorts, with particularly adverse outcomes in luminal breast cancer patients." (PMID 41047477, 2025). "Our study delineates a critical role for ARL3 in driving hormone receptor‐positive (HR+) breast cancer progression and endocrine resistance." (PMID 41047477, 2025). "This study identifies ADP‐ribosylation factor‐like protein 3 (ARL3) as a key oncogenic regulator overexpressed in ERα‐positive breast cancer cells and tissues." (PMID 41047477, 2025). "These multimodal findings establish ARL3 as a critical regulator of HR+ breast cancer progression and endocrine resistance mechanisms in vivo." (PMID 41047477, 2025). "Building on preliminary findings indicating ARL3's potential role in modulating the biological behavior of hormone receptor‐positive (HR+) breast cancer cells, we generated stable cell lines with constitutive ARL3 overexpression and CRISPR/Cas9‐mediated knockout." (PMID 41047477, 2025). "ARL3 mRNA expression was also significantly elevated in tumor tissues compared to adjacent normal counterparts, consistent with its subtype‐specific overexpression in luminal breast cancer." (PMID 41047477, 2025). "To establish ARL3 as the requisite target of A‐1331852 in HR+ breast cancer, we found that A‐1331852 exhibited no cytotoxic effects on MCF10A cells." (PMID 41047477, 2025). "Beyond its established role in ciliary trafficking, our study redefines ARL3 as a noncanonical oncoprotein with pleiotropic functions in HR+ breast cancer." (PMID 41047477, 2025).
breast carcinoma (continued). "This confirms that A‐1331852's activity in HR+ breast cancer cells is not exclusively dependent on canonical BCL‐2 family inhibition and establishes its function as an ARL3 inhibitor." (PMID 41047477, 2025).
breast tumors (1 paper, 2025). "Public dataset mining (TCGA, GSE2607) also showed elevated ARL3 levels in ERα‐positive versus ERα‐negative breast tumors, indicating ARL3 plays an important role in regulating ERα expression." (PMID 41047477, 2025).
endometrial cancer (1 paper, 2025). Primary or metastatic malignant neoplasm involving the endometrium (mucous membrane that lines the endometrial cavity). "Additionally, exploring ARL3's role in other ERα‐driven diseases, such as endometrial cancer, may expand its therapeutic relevance." (PMID 41047477, 2025).
fibrocystic disease (1 paper, 2022). "Lack of Arl3 or ARL3-dependent lipidated proteins, Inpp5e and Nphp3 in developmental cko models or Cystin-1 mutants, causes fibrocystic disease." (PMID 35832738, 2022).
glioblastoma (1 paper, 2019). The most malignant astrocytic tumor (WHO grade IV). "Here, we also observed that ARL3 influences the infiltration of immune cells in the glioblastoma microenvironment." (PMID 31234870, 2019). "Taken together, these results indicated that ARL3 influences the infiltration of immune cells into the glioblastoma microenvironment." (PMID 31234870, 2019). "To validate the conclusion that ARL3 is involved in angiogenesis in GBM, we analyzed the expression of ARL3 in the RNA-seq database of the Ivy Glioblastoma Atlas Project." (PMID 31234870, 2019).
Infertility (1 paper, 2018). "In previous studies, the expression and function of ARL3 during spermiogenesis were examined, and its potential importance in the regulation of male fertility and infertility was determined." (PMID 29298661, 2018).
malignant glioma (1 paper, 2019). A grade III or grade IV glioma arising from the central nervous system. "Since the application of standard radio- and chemo-therapy in the treatment of malignant glioma has been well established, we further analyzed the association between ARL3 expression and the response to standard radio- and chemo-therapy according to the CGGA and TCGA datasets." (PMID 31234870, 2019).
myopia (1 paper, 2025). "Myopia is also frequently associated with pathogenic variants in the ARL3 GAP RP2, which cause X-linked IRD." (PMID 40037334, 2025).
renal fibrosis (1 paper, 2026). A final common manifestation of a wide variety of chronic kidney diseases characterized by glomerulosclerosis and tubulointerstitial fibrosis. "In the context of renal fibrosis phenotype ontology (RENAL_FIBROSIS), upregulation was observed in ANTXR1, MUC1, SLC37A4, and NPHP4, while ARL3 and NPHP3 were significantly downregulated." (PMID 41573374, 2026).
tumor (5 papers, 2019 to 2025). "Strikingly, pharmacological intervention with tamoxifen revealed enhanced therapeutic responsiveness in ARL3‐deficient tumors, manifested in smaller lesion dimensions and lower tumor weights compared to tamoxifen‐treated controls." (PMID 41047477, 2025). "Immunohistochemical analysis of the HPA database showed markedly elevated expression of ARL3 in COAD tumor tissue compared with adjacent normal colon tissue." (PMID 38972051, 2025). "Targeting ARL3 with a small‐molecule inhibitor suppresses tumor growth and synergizes with endocrine therapy, highlighting its therapeutic potential." (PMID 41047477, 2025). "The rescue of OXPHOS deficits via ERα overexpression in ARL3‐knockout cells underscores the interdependency of these pathways, suggesting that ARL3‐mediated metabolic reprogramming is both ERα‐dependent and essential for tumor progression." (PMID 41047477, 2025). "ARL3 promotes tumor growth by recruiting USP10 to remove ubiquitin chains from ERα, preventing its degradation." (PMID 41047477, 2025). "Subsequent Wilcoxon tests revealed significant overexpression of ARL3 in tumor samples from the TCGA-COAD dataset, GSE39582 dataset, and GSE44861 dataset." (PMID 38972051, 2025). "In vivo tumorigenicity assays demonstrated that ARL3‐KO cells exhibited profoundly attenuated tumor growth, with xenografts displaying significant reductions in both volumetric expansion and final tumor weight compared to controls." (PMID 41047477, 2025). "In preclinical models, the small‐molecule inhibitor A‐1331852 (targeting ARL3) potently suppresses ERα‐positive tumor growth and synergizes with endocrine therapies." (PMID 41047477, 2025). "HBx increases m6A modification of circ-ARL3, a factor which binds tumour-suppressive miRNA-1305 and enhances the activity of oncogenes, resulting in the interaction of circ-ARL3 with YTHDC1 and increased biogenesis." (PMID 34767497, 2021). "Preliminary data suggest that ARL3 might influence cancer cell behavior, possibly through modulating signal transduction pathways or interacting with other proteins involved in tumor progression." (PMID 38972051, 2025). "Piperine not only downregulates ARL3 expression but also mitigates TGF-β-induced EMT, offering a dual mechanism for inhibiting tumor progression." (PMID 38972051, 2025). "By targeting ARL3 and modulating ERS pathways, Piperine offers a promising approach to inhibit tumor progression." (PMID 38972051, 2025). "Deletion of a locus on 10q24.32 containing SUFU (Suppressor of Fused), ARL3 (ADP Ribosylation Factor Like GTPase 3) and TRIM8 (Tripartite Motif Containing 8) was observed in 25/118 tumours (21%)." (PMID 34580349, 2021). "ADP-ribosylation factor-like 3 (ARL3) is a kind of small GTP-binding protein in the ADP-ribosylation factor (ARF) family belonging to the RAS superfamily, which is involved in multiple biological processes and tumor occurrence and progression." (PMID 31234870, 2019).
cancer (4 papers, 2019 to 2025). A tumor composed of atypical neoplastic, often pleomorphic cells that invade other tissues. "Piperine exerts anti-cancer effects in COAD by modulating ARL3 expression, disrupting cell cycle progression, inhibiting the EMT pathway, and regulating ERS." (PMID 38972051, 2025). "Immunohistochemical profiling also revealed distinct subcellular localization patterns; luminal carcinomas exhibited predominant cytoplasmic ARL3 accumulation, contrasting with minimal expression in triple‐negative tumors." (PMID 41047477, 2025). "The results from DAVID showed that ARL3 was involved in pathways in cancer, focal adhesion, ECM receptor interaction and leukocyte transendothelial migration." (PMID 31234870, 2019). "However, the functional role of ARL3 in cancer remains unknown." (PMID 31234870, 2019).
retinopathy (1 paper, 2025). "The phenotypic variability associated with the ARL3 c.209G > A, p.(Gly70Glu) variant shows that caution might be required in diagnosing individuals with ARL3-associated retinopathy." (PMID 40037334, 2025).
ARL3 also shares sentences with these, for which no sentence is quoted: developmental delay (2 papers); Atrophy (1); Autosomal Recessive Rod-Cone Dystrophy (1); Bardet-Biedl syndrome (1); colorectal adenocarcinoma (1); cyst (1); cystic kidney disease (1); frontometaphyseal dysplasia (1); iron deficiency (1); Meckel syndrome type 13 (1); Meckel syndrome, type 2 (1); neurodevelopmental disorder (1); osteofibrous dysplasia (1); polydactyly (1); progressive external ophthalmoplegia (1); retinal ciliopathy (1); schizophrenia (1); spondylometaphyseal dysplasia (1); Usher syndrome (1).